ELFN1 (extracellular leucine rich repeat and fibronectin type III domain containing 1)
Diseases named in the same sentence as ELFN1 in open-access papers (continued):
Sharing a sentence is not in itself a finding about the gene and the disease.
cancer (continued). "ELFN1 was found to be significantly positively correlated with CAFs and endothelial cells in most cancers." (PMID 41357574, 2025). "The initial pan-cancer analysis demonstrated increased expression of ELFN1 across 18 tumor types, including ALL, BLCA, COAD, and others." (PMID 41357574, 2025). "ELFN1 was positively correlated with the expression of a series of MMR genes in cancers such as ACC, CESC, DLBC, ESCA, GBM, HNSC-HPV-, KICH, KIRP, LGG, MESO, and OV, while it was negatively correlated in BRCA, LIHC, and SKCM." (PMID 41357574, 2025). "In this study, we aimed to elucidate the function and potential mechanism of action of ELFN1 across cancers." (PMID 41357574, 2025). "This study seeks to uncover the prognostic and immunological roles of ELFN1 in cancer, providing insights into its potential as a biomarker and immunotherapeutic target." (PMID 41357574, 2025). "Genes whose upregulation is associated with some cancers (TMEM140, ANXA10, ZNF69, CA9, LOXL2, PAGE3, ELFN1) were also on this list, as was a putative tumor suppressor (DEC1)." (PMID 33601339, 2021). "Recent studies indicate that ELFN1 may have broad functional roles in diverse biological processes, including immune regulation and cancer progression." (PMID 41357574, 2025). "The expression level of ELFN1 may provide insights into tumor development and progression in multiple cancers, including CRC, highlighting its potential utility as an effective prognostic biomarkers and immunotherapeutic targets." (PMID 41357574, 2025). "Valuable insights were provided to understand the role of ELFN1 in malignant tumors." (PMID 41357574, 2025). "The results revealed significant correlations between ELFN1 and immune regulation in various cancers, suggesting that ELFN1 may have diverse immune functions across cancers." (PMID 41357574, 2025). "This study aimed to explore the role of ELFN1 in the initiation and progression of various cancers." (PMID 41357574, 2025). "Notably, we observed that ELFN1 mRNA expression was negatively correlated with methylation in most cancers." (PMID 41357574, 2025). "ELFN1 expression was strongly correlated with CAFs in the TME and the response to immunotherapy in several cancers." (PMID 41357574, 2025). "The ESTIMATE algorithm was used to study the correlation between ELFN1 expression and the TIME in different cancer types." (PMID 41357574, 2025). "We also used TIDE database to evaluate the relationship between ELFN1 promoter methylation and cytotoxic T lymphocyte (CTL) levels in cancers such as BLCA, BRCA, BRCA-Luminal A, BRCA-Basal, TNBC, COADREAD, ESCA, GBMLGG, HNSC-HPV+, LUAD, LUSC, PAAD, SARC, STAD, UCEC, and UVM." (PMID 41357574, 2025). "Although the current evidence supports the hypothesis that ELFN1 may influence various cancer types, systematic pan-cancer analyses exploring its role are still lacking." (PMID 41357574, 2025). "Analysis using the Cancer Therapeutics Response Portal (CTRP) database revealed a negative correlation between ELFN1 levels and the IC50 values of multiple compounds, including GSK-J4, PF-3758309, omacetaxine mepesuccinate, brivanib, BRD-K35604418, oligomycin A, axitinib, and valdecoxib." (PMID 41357574, 2025). "Similarly, analysis based on the Genomics of Drug Sensitivity in Cancer (GDSC) database showed a negative correlation between ELFN1 levels and the IC50 values of axitinib, pazopanib, elesclomol, YK 4-279, TW 37, midostaurin, and bleomycin (50 μM)." (PMID 41357574, 2025).
tumor (3 papers, 2021 to 2025). "GO and KEGG pathway analyses revealed that ELFN1 is involved in regulating multiple tumor-associated pathways, including those related to enzyme and GTPase activities." (PMID 41357574, 2025). "The molecular function (MF) enrichment analysis revealed that ELFN1 is associated with kinase regulatory activity and transmembrane transporter activity, suggesting its role in tumor pathogenesis." (PMID 41357574, 2025). "Instead, studies have shown that ELFN1 is expressed in CAFs and endothelial cells in various tumor tissues." (PMID 41357574, 2025). "To better understand the main cell types expressing ELFN1 in the tumor microenvironment, we performed single-cell analysis of ELFN1 expression across 79 tumor single-cell datasets." (PMID 41357574, 2025). "Supporting its role in TIL resistance, enhanced ELFN1 methylation in baseline tumor tissues correlates with treatment response in these patients." (PMID 41357574, 2025). "We further investigated the potential immunoregulatory functions of ELFN1 in tumor immunity." (PMID 41357574, 2025). "We analyzed ELFN1 expression across 33 tumor types at different clinical stages and subtypes." (PMID 41357574, 2025). "In CRC cells, ELFN1 knockdown significantly inhibited tumor proliferation, migration, and motility." (PMID 41357574, 2025). "However, this discovery requires further in vitro and in vivo experimental exploration to elucidate the specific mechanisms by which ELFN1 functions during tumor progression and immunotherapy, which is crucial for advancing immune-based therapeutic strategies for tumors." (PMID 41357574, 2025). "We next compared ELFN1 expression between tumor tissues and their corresponding normal tissues using the TCGA and GTEx databases." (PMID 41357574, 2025). "Given its diagnostic potential, we next evaluated the prognostic relevance of ELFN1 in predicting overall survival (OS), disease-specific survival (DSS), disease-free interval (DFI), and progression-free interval (PFI) across 33 tumor types using the TCGA database." (PMID 41357574, 2025). "In this study, ELFN1 was found to correlate with TMB and MSI in certain tumor types, though the correlations were not highly significant." (PMID 41357574, 2025).
ELFN1 also shares sentences with these, for which no sentence is quoted: autism spectrum disorder (3 papers); autism (2); Intellectual disability (2); neurodevelopmental disorder (2); post-traumatic stress disorder (2); schizophrenia (2); Alzheimer disease (1); breast carcinoma (1); cervical squamous cell carcinoma (1); cholangiocarcinoma (1); Epileptic encephalopathy (1); gastric cancer (1); kidney chromophobe (1); lung adenocarcinoma (1); lymphoma (1); migraine (1); myopia (1); Obesity (1); Pan (1); prostate adenocarcinoma (1); prostate carcinoma (1); sarcoma (1); Seizure (1); uterine corpus endometrial carcinoma (1); Wilms tumor (1).